RNU6-1065P (RNA, U6 small nuclear 1065, pseudogene)
Gene: Small nuclear RNA gene on chromosome 17 (10,857,899 to 10,858,004, reverse strand). Ensembl gene ENSG00000207242.
Homologues: Orthologues: chimpanzee U6 (99% identical), macaque U6 (93% identical). Paralogues in human: RNU6-1024P (88% identical), RNU6-1152P (87% identical), RNU6-905P (87% identical), RNU6-1060P (86% identical), RNU6-15P (86% identical), RNU6-19P (86% identical), RNU6-41P (86% identical), RNU6-820P (86% identical), RNU6-1131P (85% identical), RNU6-1181P (85% identical), RNU6-12P (85% identical), RNU6-13P (85% identical), and 1289 more.